UBASH3A (ubiquitin associated and SH3 domain containing A)
Diseases named in the same sentence as UBASH3A in open-access papers (continued):
Sharing a sentence is not in itself a finding about the gene and the disease.
Graves disease (1 paper, 2011). Graves' disease is an autoimmune disorder that leads to overactivity of the thyroid gland (hyperthyroidism).It is caused by an abnormal immune system response that causes the thyroid gland to produce too much thyroid hormones. "In the present report we illustrate that this strategy is successful with the identification of two new candidate genes for Graves' disease susceptibility, BACH2 and UBASH3A." (PMID 21829393, 2011). "Analysis of the TPOA-associated loci in 2,477 cases with Graves' disease identified two new AITD loci (BACH2 and UBASH3A)." (PMID 21829393, 2011). "TPOA are commonly detected in Graves' disease patients and, therefore, the TPOA- associated SNPs located in the genes RASGRP1, UBASH3A and BACH2 that have not been previously tested for Graves' disease association are strong Graves' disease candidates." (PMID 21829393, 2011).
lacrimal gland disease (1 paper, 2020). "Together, these studies suggest that Ubash3a is not required for Treg-mediated prevention of spontaneous male salivary gland disease or female lacrimal gland disease." (PMID 32694640, 2020).
Neonatal sepsis (1 paper, 2021). Systemic inflammatory response to infection in newborn babies. "Interestingly, we found that the promoters of genes involved in T-cell regulation (i.e., CD3D, CD3G, UBASH3A, SIT1, and TXK) were hypermethylated in neonatal sepsis compared to controls, thereby resulting in decreased expression." (PMID 33659006, 2021).
primary sclerosing cholangitis (1 paper, 2024). "In this work, colocalisation analyses nominate likely primary sclerosing cholangitis effector genes and biological mechanisms at five non-coding (UBASH3A, PRKD2, ETS2 and AP003774.1/CCDC88B) and one coding (SH2B3) primary sclerosing cholangitis loci." (PMID 39505854, 2024).
Sjögren syndrome (1 paper, 2020). "In summary, we generated UBASH3A-deficient NOD mice and characterized them for the development of T1D and Sjögren syndrome-like manifestations." (PMID 32694640, 2020). "Of note, despite the similar T1D-promoting effects of disruption of Ubash3a in male and female NOD mice, the effects on Sjögren syndrome-like manifestations only enhanced female-specific salivary gland inflammation but did not alter male-specific lacrimal gland inflammation." (PMID 32694640, 2020). "To determine if disruption of Ubash3a affected Sjögren syndrome-like manifestations that spontaneously develop in NOD mice, we quantified inflammation in salivary and lacrimal glands of 10-week-old pre-diabetic wild-type NOD and Ubash3a-m3 mice." (PMID 32694640, 2020).
thymoma (1 paper, 2024). A neoplasm arising from the epithelial cells of the thymus. "Thymoma was the only tumor in which higher UBASH3A was significantly associated with worse patient outcome." (PMID 38461240, 2024).
tumor (6 papers, 2018 to 2024). "In contrast to UBASH3B, knockdown of FLI1 in erythroleukemia cells upregulates UBASH3A expression, raising the possibility of a tumor suppressor function for this variant." (PMID 38461240, 2024). "Thus, the combined oncogenic and tumor suppressor activities of UBASH3A and UBASH3B and their downstream effectors influence leukemogenesis." (PMID 38461240, 2024). "Since HSPA1B is negatively regulated by both UBASH3A and UBASH3B, its tumor suppressor activity is dependent upon balance between the level of these UBASH3 proteins, negatively and positively regulated by FLI1, respectively." (PMID 38461240, 2024).
infection (5 papers, 2014 to 2025). The state of being infected such as from the introduction of a foreign agent such as serum, vaccine, antigenic substance or organism. "Analysis of CD6 binding proteins revealed that infection-induced upregulation of Ubash3a, a negative regulator of T cell receptor (TCR) signaling, was hindered in CD6-deficient lymph nodes." (PMID 39679790, 2025).
cancer (4 papers, 2020 to 2024). A tumor composed of atypical neoplastic, often pleomorphic cells that invade other tissues. "Accordingly, overexpression of UBASH3A in different cancers was predominantly associated with good prognosis." (PMID 38461240, 2024). "However, higher expression of UBASH3A was found to be a good prognosis marker for patient survival in most tumors, further supporting its anti-cancer activity." (PMID 38461240, 2024). "Interestingly, UBASH3A expression was both induced and reduced relative to normal cells in various cancers." (PMID 38461240, 2024). "To examine a broader role of these UBASH genes in cancer, we examined the correlation between FLI1 and UBASH3A or UBASH3B in the TCGA database by GEPIA2." (PMID 38461240, 2024). "Selected candidate genes, i.e., UBASH3A, MYH13, UTP11L, and PAX7, were further evaluated using protein expression analysis but no alterations of cancer-related pathways were observed." (PMID 35625741, 2022).
UBASH3A also shares sentences with these, for which no sentence is quoted: colitis (2 papers); autoimmune thyroid disease (1); Behçet’s disease (1); Breast invasive Carcinoma (1); colon adenocarcinoma (1); COVID-19 (1); diffuse large B-cell lymphoma (1); disseminated candidiasis (1); experimental autoimmune encephalomyelitis (1); Immunodeficiency (1); Obesity (1); ovarian carcinoma (1); prostate carcinoma (1); renal cell carcinoma (1); salivary gland disease (1); schizophrenia (1); Skin cutaneous melanoma (1); T-cell lymphoma (1); type 2 diabetes (1).